PTH (parathyroid hormone)
Diseases named in the same sentence as PTH in open-access papers (continued):
Sharing a sentence is not in itself a finding about the gene and the disease.
hyperphosphatemia (continued). "It showed statistically significant differences in the PTH and Scr (p < 0.05) between hyperphosphatemia and non-hyperphosphatemia CAPD patients." (PMID 37122336, 2023). "During follow-up through a local hospital, the patient presented with normal serum total calcium levels, hyperphosphatemia and elevated parathyroid hormone (PTH)." (PMID 37794407, 2023). "As a result, in patients with CKD, high levels of FGF-23 attenuate hyperphosphatemia, decrease levels of active vitamin D, and inhibit PTH synthesis and secretion." (PMID 36293076, 2022). "In human medicine, plasma FGF 23 and PTH concentrations increase in CKD patients before the development of hyperphosphatemia." (PMID 36077967, 2022). "Increased serum phosphate is known to affect bone metabolism directly and indirectly through the development of adaptive hormonal mechanisms aimed at preventing hyperphosphatemia, such as the increase in PTH and FGF23 and the reduction in calcitriol." (PMID 35080671, 2022). "Compared to the mice fed a standard phosphate diet, mice on a high phosphate diet developed hyperphosphatemia (on average 0.5 mM (26%) higher), clearly higher PTH levels and a tendency to higher FGF23 levels." (PMID 35511366, 2022). "Systemic FGF-23 levels rapidly increase as renal function declines, and this occurs before an increase in other markers, such as parathyroid hormone, vitamin D or even phosphorus, likely as a compensatory mechanism to prevent hyperphosphatemia after ARF." (PMID 35216382, 2022). "Chronically raised levels of PTH initiate severe bone resorption, further intensifying hyperphosphatemia, as the normal ‘storage container’ feature of the skeleton is lost." (PMID 36293083, 2022). "The results showed that the risk factors for sleep disorders in patients were age ≥60 years, hypercalcium and hyperphosphatemia, substandard PTH, and high CRP." (PMID 34867112, 2021). "Hyperphosphatemia, decreased 1,25-dehydroxyvitamin D, decreased serum calcium, and increased parathyroid hormone (PTH) levels were observed." (PMID 34046371, 2021). "Studies on animal models demonstrated that CKD-MBD, apart from elevated levels of FGF23, PTH, reduced Klotho hyperphosphatemia, osteodystrophy, vascular calcification, and cardiac hypertrophy, was characterized by the stimulation of ActRIIA." (PMID 34208727, 2021). "Newer therapies, based on PTH analogues, by contrast, are able to restore normal phosphate excretion in a few days, thus avoiding hyperphosphatemia." (PMID 34884774, 2021). "Low levels of the vitamin D hormone, as well as hyperphosphatemia induce parathyroid hormone (PTH) secretion." (PMID 34290280, 2021). "Late in the course of CKD, phosphorus retention and overt hyperphosphatemia, together with skeletal resistance to the calcemic action of PTH, can also affect calcium metabolism adversely and further increase PTH secretion among patients with more advanced CKD." (PMID 32367309, 2020). "Hyperphosphataemia increases the secretion of PTH by the parathyroid glands and FGF23 by osteocytes, osteoblasts, and osteoclasts." (PMID 32132645, 2020). "This disturbance appears in patients with ESRD and is characterized by extremely high levels of PTH, as well as hypercalcemia, hyperphosphatemia, and elevated levels of osteolysis and osteogenesis indicators." (PMID 32823917, 2020). "In patients on dialysis, hyperphosphatemia directly stimulates PTH secretion and maintains a persistent stimulus for parathyroid hyperplasia." (PMID 32913635, 2020). "Clinical studies have indicated that high PTH levels, hyperphosphatemia, and high urea nitrogen levels increase the intensity of pruritus." (PMID 33104746, 2020). "A direct effect of hyperphosphatemia on inducing increased PTH concentrations is possible as postulated in cats." (PMID 32582784, 2020). "The management of SHPT is based on avoiding hyperphosphatemia and decreasing PTH levels by administrating calcimimetics and, when needed, VDR activators." (PMID 32913635, 2020).
hyperphosphatemia (continued). "The hyperphosphatemia observed in PT-PTH1RKL−/− mice was associated with elevated circulating FGF23, PTH, decreased circulating 1,25D and increased Npt2a." (PMID 32982979, 2020). "A high phosphate diet was required to induce severe hyperphosphatemia as well as marked elevation of PTH and FGF‐23 in the CKD rats." (PMID 33190417, 2020). "Biochemical investigations showed persistent low serum corrected calcium levels with hyperphosphataemia, hypomagnesaemia, low parathyroid hormone levels, hypercalciuria, and low total 25-hydroxy vitamin D levels." (PMID 31660939, 2019). "A high percentage of subjects displayed hyperphosphataemia and PTH values outside the recommended range." (PMID 31218231, 2019). "Although the pathogenic basis of hyperphosphatemia in CKD is renal insufficiency, the clinical manifestations of CKD-MBD are mainly due to the adaptive response mediated by PTH and FGF23." (PMID 30944300, 2019). "In imaging studies, observations of metabolic bone disease with hyperphosphatemia, hypoxia, increased levels of parathyroid hormone (PTH) and radiological disorders, normocytic and normochromic anemia, and reduced kidney size (<8.5 cm) strongly favor CKD." (PMID 30858939, 2019). "He had persistent low serum corrected calcium levels with hyperphosphatemia, mild hypomagnesaemia, and low parathyroid hormone levels." (PMID 31660939, 2019). "Laboratory revealed hypoparathyroidism with PTH < 0.3 pmol/L (normal 1.5–7.6), total calcium 1.20 mmol/L (normal 2.15–2.50), 25-OH-vit D 65 nmol/L (normal 50–178), and hyperphosphataemia 2.0 mmol/L (normal 0.7–1.7)." (PMID 29380231, 2018). "Hyperphosphatemia is a main risk factor aggravating the severity of PTG hyperplasia and dialysis vintage and serum PTH level are also in a relation with nodular hyperplasia." (PMID 30513912, 2018). "Hyperphosphatemia indirectly increased parathyroid hormone (PTH) secretion to reduce serum calcium by different possible pathways." (PMID 29476104, 2018). "PTH secretion is very sensitive to its primary stimulus, serum calcium levels, and is also responsive to hyperphosphatemia." (PMID 30109232, 2018). "Laboratory tests revealed hypocalcemia, hyperphosphatemia, and low serum parathyroid hormone (sPTH)." (PMID 27384690, 2017). "The two most important primary reasons to start cinacalcet were to reduce PTH in patients with hyperphosphatemia (56.3%, n = 174) or to reduce PTH in patients with normophosphatemia and normocalcemia (21.7%, n = 67)." (PMID 28091752, 2017). "Laboratory tests showed biochemical findings similar to the aforementioned: low level of s PTH, 25-OH-vitamin D, and alkaline phosphatase; hyperphosphatemia; and clearly decreased levels of total and ionized calcium." (PMID 27384690, 2017). "As renal function declines patients uniformly develop hyperphosphatemia, increased levels of parathyroid hormone (PTH) and fibroblast growth factor 23 (FGF23)." (PMID 29263429, 2017). "FGF23 knockout mice have normal serum PTH but display hyperphosphatemia, consistent with the phosphaturic effect of PTH being dependent on the presence of FGF23158." (PMID 29043081, 2017). "Hyperphosphatemia, increased PTH level, inflammation, endothelial dysfunction, oxidative stress are also common non-traditional markers of high CV risk in dialysis patients." (PMID 28710615, 2017). "The patient exhibited normocalcemia (2.37 mmol/L) and hyperphosphatemia (2.42 mmol/L) with elevated intact parathyroid hormone (707,000 μg/L)." (PMID 29047366, 2017). "At this time, laboratory analyses revealed a mild hyperphosphatemia with normocalcaemia and a slight elevation of PTH levels." (PMID 27415614, 2016). "Subclinical hypothyroidism was present in 70%, increased parathormone (PTH) in 83%, and hyperphosphatemia in 50%." (PMID 27467896, 2016). "The results showed reduced hemoglobin, hyperphosphatemia, increased plasma PTH and FGF-23, and decreased plasma 25OH-D3 and 1,25-(OH)2D3 concentrations." (PMID 27658028, 2016).
hyperphosphatemia (continued). "Hyperphosphataemia stimulates parathyroid glands to increased secretion of parathyroid hormone (PTH), which in turn increases the release of phosphate from the bone, contributing to further accumulation of phosphate in serum." (PMID 25145866, 2014). "Most important, epidemiological studies have shown that increased levels of FGF-23, PTH and low levels of 1,25(OH)2D3 are features that precede hyperphosphatemia during progression to CKD." (PMID 25222475, 2014). "This reaction is stimulated by PTH, calcitonin, and hypophosphatemia and inhibited by calcium, 1,25D, and hyperphosphatemia." (PMID 24716007, 2014). "Serum 1,25 dihydroxyvitamin D3 was inappropriately normal in the setting of hyperphosphatemia and serum intact PTH was low." (PMID 25249269, 2014). "In some patients, it appears that the development of hyperphosphatemia has rendered previously therapeutic doses of calcitriol ineffective at suppressing PTH (serum phosphorus > 2.6 mmol/L [> 8.0 mg/dL])." (PMID 23566108, 2013). "Both parathyroid hormone (PTH), the main stimulus of the rate-limiting enzyme 1alpha-hydroxylase, and hyperphosphatemia, the main inhibitory signal, are modified in CKD." (PMID 23202302, 2012). "Phosphate binders are approved for the treatment of hyperphosphatemia in patients receiving maintenance dialysis based on their efficacy on the endpoint of phosphorus and possibly PTH control." (PMID 21324193, 2011). "Decreases in serum calcium (Ca) (hypocalcemia) and prolonged increases in serum phosphate (hyperphosphatemia) stimulate the parathyroid gland to secrete PTH from its storage granules." (PMID 20204178, 2010). "By 17 months of age, he manifested osteoma cutis, psychomotor retardation, obesity, brachydactyly and resistance to PTH with normocalcemia and mild hyperphosphatemia." (PMID 21274302, 2009). "Hyperphosphatemia can directly increase PTH synthesis, stabilize PTH mRNA, promote parathyroid hyperplasia, and decrease the calcium receptor." (PMID 19924035, 2009). "Low and high PTH and hyperphosphatemia as well facilitate VC." (PMID 40136613, 2025). "The other two related patients showed normal calcium concentrations (2.56 mmol/L and 2.44 mmol/L), mildly lowered parathyroid hormone concentrations (12.3 ng/L and 11.2 ng/L), and elevated phosphate concentrations (3.26 mmol/L and 2.87 mmol/L), suggesting familial hyperphosphatemia." (PMID 41180951, 2025). "Consequently, electrolyte imbalances—such as hyperphosphatemia, often accompanied by elevated serum parathyroid hormone levels—commonly arise in patients undergoing hemodialysis." (PMID 41140700, 2025). "Hyperphosphatemia contributes to CAC development through multiple mechanisms: Elevated serum phosphorus directly stimulates parathyroid hormone (PTH) secretion, promotes osteoblast differentiation, and facilitates pathological calcium-phosphorus deposition in the vascular wall." (PMID 40314886, 2025). "Elevated intact PTH is an indicator of hyperphosphatemia in CKD." (PMID 40573061, 2025). "In patients with CKD and hyperphosphataemia, the phosphaturic effect of PTH is partly blunted." (PMID 37660247, 2024). "Additionally, hyperphosphatemia stimulates the production of parathyroid hormone (PTH), which is the primary regulator of the Receptor Activator of Nuclear Factor kappa B (RANK)/RANK ligand (RANKL)/osteoprotegerin (OPG) system." (PMID 38891922, 2024). "The mechanism behind this relationship is unclear; it has been suggested that the increase in FGF-23, following the increase in PTH and hyperphosphatemia, may induce a worsening of renal function and a progression towards dialysis." (PMID 36678208, 2023). "Moreover, SGLT2i treatment alters renal handling of mineral homeostasis, thus increasing parathyroid hormone with hyperphosphatemia alongside promoting calcinuria." (PMID 38139208, 2023).
hyperphosphatemia (continued). "For example, in CKD, the classic hypothesis suggested that there was a trade-off between PTH for phosphorus level normalization and that this process occurred before hyperphosphatemia." (PMID 36904234, 2023). "In advanced stages of kidney disease, when the excretory function of the kidneys is significantly reduced, elevated levels of PTH, which can act as a uremic toxin in kidney failure, cannot maintain normal phosphate levels, and hyperphosphatemia becomes evident." (PMID 35204237, 2022). "Therefore, the suppression of renal 1,25(OH)2D production makes FGF23 a more effective hormone for counteracting hyperphosphatemia compared with PTH." (PMID 34950827, 2021). "However, for reasons of technical feasibility, mimicking circadian PTH secretion failed and hyperphosphatemia was observed during the continuous pump administration, as opposed to the bi-daily sub-cutaneous administration." (PMID 34820344, 2021). "MBDs include changes in serum calcium (Ca2+) concentration, increased serum phosphate levels (hyperphosphatemia), reduced serum levels of active vitamin D, secondary increase of parathyroid hormone (PTH), augmented FGF-23 systemic levels, and reduced levels of the antiaging factor Klotho." (PMID 34867481, 2021). "PTH elevation may represent a compensatory response to hyperphosphatemia and increasing bone resistance to PTH." (PMID 34853790, 2021). "Populational studies have pointed out that, in CKD patients, the increase in FGF-23 and PTH, accompanied by the decrease in 1,25 dihydroxyvitamin D3, anticipate hyperphosphatemia, which is often observed in these patients and is usually related to a higher mortality risk among them." (PMID 35056905, 2021). "Phosphate load may lead to increased fibroblast growth factor 23, decreased vitamin D, increased intact parathyroid hormone, and decreased klotho; such a vicious cycle is likely activated even before hyperphosphatemia occurs." (PMID 33459122, 2021). "On the other hand, Familiar Tumor Calcinosis (FTC), a rare autosomal recessive disorder, is a mirror image of FGF23 related hypophosphatemic diseases, featured by hyperphosphatemia, inappropriately elevated 1,25(OH)2D3and PTH levels and ectopic calcified masses." (PMID 34068220, 2021). "Moreover, PTH determination is needed in the monitoring of the efficacy of the treatment for hyperphosphatemia or RHPT." (PMID 33348538, 2020). "Our study revealed that the elevated level of FGF-23 went ahead hyperphosphatemia and elevated PTH." (PMID 33379157, 2020). "To assess whether the rise in PTH secretion observed in hyperphosphatemia was mediated by the CaSR, we compared PTH secretion levels from control and CaSR-knockout (KO Casr) murine parathyroid glands." (PMID 31619668, 2019). "In humans, increased FGF23 levels appear before a detectable rise in PTH and hyperphosphataemia, suggesting that an increase in FGF23 may be the earliest sign of disordered mineral metabolism in CKD." (PMID 30393837, 2019). "It has been suggested that it may result from hyperphosphatemia, osteocytic resistance to the effects of PTH, impaired binding of SCL by its specific receptors, or increased extraskeletal production." (PMID 31847451, 2019). "Then in the hyperphosphatemia of CKD, Pi-mediated stabilization of the CaSR’s inactive conformation would elicit chronically increased PTH release as the damaged kidneys fail to excrete the Pi, leading to SHPT, and in turn to further bone loss and hyperphosphatemia." (PMID 31619668, 2019). "Hyperphosphataemia as a result of increased PT reabsorption of Pi occurs in hypoparathyroidism, acromegaly, treatment with bisphosphonates and following vitamin D toxicity, with hypercalcaemia also reducing Pi excretion and PTH secretion." (PMID 30393837, 2019). "Elevated PTH secretion levels together with hyperphosphatemia are major complications of CKD." (PMID 31619668, 2019).
hyperphosphatemia (continued). "One hypothetic explanation is that hyperphosphatemia is prevented until the later stages of CKD by parathyroid hormone (PTH) and fibroblast growth factor-23 (FGF-23), which in turn suppress renal phosphate reabsorption and augment renal phosphate excretion in these patients." (PMID 30301260, 2018). "In patients with CKD stages 3–5D and hyperphosphatemia, we suggest restricting the dose of calcium-based phosphate binders in the presence of arterial calcification (2C) and/or adynamic bone disease (2C) and/or if serum PTH levels are persistently low (2C)." (PMID 30236082, 2018). "Hyperphosphatemia stimulates even more PTH secretion, perpetuating further a maladaptive response." (PMID 30109232, 2018). "However, transient hyperphosphatemia was noted in cinacalcet-treated mice, which was likely to be a consequence of suppressed PTH secretion." (PMID 29046478, 2017). "PHP-Ia patients have a reduced phosphatidic response to PTH, which leads to hyperphosphatemia." (PMID 27425121, 2017). "Biochemically, the earliest features suggestive of PHP type IA in our population were subclinical hypothyroidism characterized by high TSH with normal or low fT4 present in 70% of cases, followed by increased PTH (83% of cases) and hyperphosphatemia (50% of cases)." (PMID 27467896, 2016). "However, in the PTX+CKD rats in our study, a low mean serum FGF-23 level was noted despite hyperphosphatemia, which was likely related to low mean circulating PTH levels." (PMID 26186634, 2015). "In patients with CKD stages 3–5D and hyperphosphatemia, we suggest restricting the dose of calcium based phosphate binders in the presence of arterial calcification and/or adynamic bone disease and/or if serum PTH levels are persistently low." (PMID 24451311, 2014). "Therefore, the treatment of hyperphosphatemia clinically controls Pi levels, however, is also required to control the serum Ca, PTH and FGF-23 levels, as dietary Pi restriction and Pi removal via blood purification alone are insufficient." (PMID 24669256, 2014). "However, we have previously reported lower bone volume in Nx+PTx rats fed with high P diet (1.2%) that developed hyperphosphatemia in presence of normal PTH." (PMID 24236156, 2013). "Besides, the prominent PTH along with severe medial calcification and hyperphosphatemia well mimic the condition of ESRD patients who were eligible for treatment of Lanthanum carbonate." (PMID 24330832, 2013). "Extreme elevations of PTH levels along with hyperphosphatemia could result from an abnormal form of plasma PTH." (PMID 23865435, 2013). "Several factors may be responsible for cardiac disease in ESRD, such as hypertension, anemia, hyperphosphatemia, and a high parathyroid hormone (PTH)." (PMID 23915058, 2013). "Interestingly, Dmp1−/−kl/kl mice show a dramatic improvement of rickets and an identical serum biochemical phenotype to kl/kl mice (extremely high FGF23, hyperphosphatemia and reduced parathyroid hormone (PTH) levels)." (PMID 22879941, 2012). "Higher amounts of parathyroid hormone and alkaline phosphatase in HD group might be a result of poorer control of hyperphosphatemia in the HD group." (PMID 20535268, 2010). "In addition, other factors such as continued phosphate reabsorption by PT, decreased phosphate uptake into bone due to low 1,25(OH)2D levels, and ongoing phosphorus release from bone by elevated PTH further exacerbate hyperphosphatemia, thus creating a vicious cycle." (PMID 40362897, 2025). "Furthermore, hyperphosphatemia not only directly impacts PTH secretion but also suppresses the renal production of 1,25-dihydroxyvitamin D (calcitriol), a crucial hormone for intestinal calcium absorption, thereby exacerbating bone mineral loss and further disrupting mineral homeostasis." (PMID 40573160, 2025). "Furthermore, hyperphosphatemia correlates with PTH and Ca, which are components of MBD10,31." (PMID 37363538, 2023).